INS (insulin)
Diseases named in the same sentence as INS in open-access papers (continued):
Sharing a sentence is not in itself a finding about the gene and the disease.
Hyperglycemia (continued). "There should be a low threshold for starting insulin therapy for young people with LAD exhibiting evidence of fasting or postprandial hyperglycemia with rising glycated hemoglobin levels while on a trial of diet control or oral anti-diabetic therapy." (PMID 39329041, 2024). "Glucose tolerance and insulin tolerance tests (GTT and ITT) confirmed that HFHSD-fed male mice had typical symptoms of T2D: hyperglycemia and impaired insulin sensitivity." (PMID 39337631, 2024). "Only, SeEx-C NPs (either 10 or 20 mg/kg b.w.)have succeeded in decreasing hyperglycemia and increasing insulin level in diabetic treated group." (PMID 38461158, 2024). "Hyperglycaemia and inflammation hampers insulin signalling and eNOS activity within endothelial cells." (PMID 38774996, 2024). "For most patients who develop hyperglycemia, initiation of medical therapy with metformin alone is sufficient, followed by staged treatment with incretin-based therapies and insulin, as required, to achieve and maintain glycemic control." (PMID 38577574, 2024). "AMPK activation can increase glucose uptake and decrease hyperglycaemia by promoting energy expenditure, together with the increase in insulin sensitivity to attenuate metabolic stresses." (PMID 38229038, 2024). "Taken together, the KcnK16 L114P mouse model shows disrupted glucagon and insulin secretion leading to fasting hyperglycemia and glucose intolerance, which provides confirmation that TALK-1 gain-of-function mutations likely cause MODY." (PMID 38700926, 2024). "PLX-5622 treatment depleted hypothalamic microglia by >95% across animals, without body weight gain or food intake modification and prevented induction of both the 3d HFD insulin hypersecretion and post-absorptive hyperglycemia." (PMID 39625057, 2024). "Impaired insulin signaling in the liver leads to hyperglycemia and hyperinsulinemia, and upregulated insulin further activates de novo lipogenesis pathway." (PMID 39411175, 2024). "When insulin-sensitizing action diminishes, excess insulin is the only resort to reduce hyperglycemia." (PMID 39457235, 2024). "Their known mechanisms of action include slowing gastric transit, promoting hyperglycemia-induced insulin secretion, and suppressing glucagon secretion in hyperglycemia." (PMID 39238749, 2024). "Hepatic mitochondrial dysfunction increases glucose output, whereas skeletal muscle mitochondrial dysfunction decreases glucose uptake, both of which together lead to increased hyperglycaemia and insulin resistance." (PMID 39634184, 2024). "Hyperglycemia and IR have also been proposed to impair hydrogen ion buffering, so urinary pH has also been regarded as a marker of renal insulin sensitivity." (PMID 39416649, 2024). "Dehydration-induced acute kidney injury and the omission of insulin injections for blood sugar control contributed to hyperkalemia and hyperglycemia with diabetic ketoacidosis in this patient." (PMID 38799756, 2024). "In this study, hearts from diabetic mice, which received 4 weeks of insulin treatment after 4 weeks of hyperglycemia, were subjected to isolation of subcellular fractions." (PMID 39539089, 2024). "Circulating insulin concentrations were unperturbed by IUGR under resting conditions but exhibited a 40% disparity under hyperglycemia, demonstrating impaired stimulus–secretion coupling." (PMID 38535316, 2024). "In contrast, transplantation of islets overexpressing SREBP1c restored insulin levels and alleviated hyperglycemia." (PMID 39130628, 2024). "Given the elevated insulin levels >2000 uIU/mL and episodes of hyperglycemia and hypoglycemia off insulin therapy, insulin auto-antibody labs were sent." (PMID 39347250, 2024). "This indicated that the MSTZ model had a more severe effect on insulin secretion, leading to more severe hyperglycemia, than the LSTZ/HFD." (PMID 38856757, 2024).
Hyperglycemia (continued). "The resolution of hyperglycemia with insulin treatment is also shown to decrease circulating proinflammatory cytokines TNF-α, IL6, IL-1β, and the chemokine IL-8 to or near normal control levels." (PMID 38550920, 2024). "Aberrant gluconeogenesis is considered among primary drivers of hyperglycemia under insulin resistant conditions, with multiple studies pointing towards epigenetic dysregulation." (PMID 38745315, 2024). "The insulin resistance in trophoblastic cells leads to maternal hyperglycemia and alters the nutrient transfer to the fetus." (PMID 39519193, 2024). "Benfotiamine reduces glucose toxicity caused by hyperglycemia in T2DM by activating glucose metabolism and insulin synthesis." (PMID 38612580, 2024). "The overall proportion of patients who were treated with paracetamol for fever, and insulin for hyperglycaemia, has improved in clinical practice both before and after the guideline recommendation when compared to each of the FeSS Intervention studies." (PMID 39507681, 2024). "Aditionally, chronic hyperglycaemia increases IR by inducing glucotoxicity, which participates in reducing peripheral glucose uptake; moreover, intensive insulin therapy in T1D patients was shown to increase the degree of insulin sensitivity." (PMID 38341550, 2024). "The actions of naringenin include improving hyperglycemia, insulin sensitivity, pancreatic cell performance, and lipid profile." (PMID 39062550, 2024). "Pregnant women with hyperglycemia through the placenta will stimulate the production of a large amount of insulin secretion of the fetus to be able to make full use of blood sugar, and promote the synthesis of protein and fat, so that the fetus grows larger." (PMID 38660519, 2024). "This necessitates intensive medical therapy and often requires adjusted insulin administration to prevent threatening hyperglycemia for the fetus." (PMID 38396408, 2024). "Several educational sessions are addressed, including blood glucose monitoring, insulin injections, nutritional education, carbohydrate counting, and recognizing the signs and symptoms of hyperglycemia and hypoglycemia." (PMID 39408305, 2024). "Patients’ expectations regarding insulin pumps revolve primarily around the dose of insulin, the prevention of episodes of hypoglycemia and hyperglycemia, and the reduction of the number of injections." (PMID 39376804, 2024). "While increasing insulin doses is a common approach to managing hyperglycemia, it’s essential to also assess the adequacy of carbohydrate administration, especially when patients require high insulin doses for more than 24 h." (PMID 39227957, 2024). "They suggest that the most likely mechanism is reduced maternal insulin secretion, resulting in maternal hyperglycemia and increased insulin-mediated fetal growth." (PMID 38612849, 2024). "Diabetes has become one of the most prevalent and serious chronic diseases, and it is a metabolic disorder characterized by hyperglycemia, resulting from impaired insulin secretion and/or action." (PMID 39338366, 2024). "We then sought to determine if exposing cells to high glucose media (20 mM), to mimic hyperglycaemia, would have any effect on INS expression induced by psEVs." (PMID 39432712, 2024). "Trauma induces a stress response characterized by the release of catecholamines and glucocorticoids, which increase hepatic glucose production and reduce insulin sensitivity, leading to hyperglycemia." (PMID 39061646, 2024). "DM is a group of metabolic diseases characterized by hyperglycemia, resulting from defects in insulin production and/or insulin action and impaired carbohydrate, lipid, and protein metabolism." (PMID 39655056, 2024). "This situation of hyperglycemia is explained by the fact that patients are unable to metabolize glucose following the defect of insulin secretion by the Langerhans beta cells of the pancreas." (PMID 38738016, 2024).
Hyperglycemia (continued). "All probands presented in severe state of DKA, seizures and fluctuating hyperglycemia and hypoglycemia with insulin therapy." (PMID 40302952, 2024). "In the multiple dose STZ-diabetic (MDSD), daily i.p. injections of GABA(20 μmol/mouse, i.p.)for 7-days prior to STZ prevented hyperglycemia, increased serum insulin, decreased glucagon, restored β-cell mass and normalized α-cell mass." (PMID 39619323, 2024). "In another study conducted during a winter camp, the use of Tandem Control-IQ HCLS (Control-IQ) demonstrated improved glycemic control and reduced exposure to hyperglycemia compared to sensor-augmented insulin pumps in children and adolescents." (PMID 39064653, 2024). "There was also an increase in NPH insulin prescription, which is another strong point of this intervention’s results because guidelines suggest that hospital hyperglycemia should be managed with either basal insulin or basal-bolus insulin as the main agents." (PMID 39420910, 2024). "Chronic hyperglycemia is implicated in direct impairment of the PI3K/AKT signaling pathway, which is a pivotal step in insulin action." (PMID 38543160, 2024). "The presence of hyperglycemia and ketonemia required prompt attention through insulin therapy with regular blood glucose monitoring." (PMID 39712682, 2024). "Adherence to the diet is understood as following the recommended guidelines, and it is observed that a mismatch between carbohydrate intake and insulin can result in hypo- or hyperglycemia." (PMID 38541320, 2024). "Visfatin is upregulated by hypoxia, inflammation and hyperglycemia and downregulated by insulin, somatostatin and statins." (PMID 39424616, 2024). "We and other groups have already shown that CK2 inhibition reduces hyperglycaemia by increasing insulin expression and secretion." (PMID 38503901, 2024). "Hyperglycemia decreases circulating Sfrp5 concentrations during oral glucose tolerance tests (OGTT) in healthy and insulin-sensitive individuals, suggesting a direct effect of hyperglycemia." (PMID 39339733, 2024). "Combined hyperglycemia- and arginine-stimulated β-cell secretory capacity was calculated as the insulin AUC during the 30 min after the arginine bolus." (PMID 38892122, 2024). "This study aimed to evaluate the biological consequences of insulin oxidation in the context of hyperglycemia." (PMID 39378614, 2024). "Insulin sensitivity decreases due to continual secretion, which leads to hyperinsulinemia in an effort to compensate for and prevent hyperglycemia." (PMID 38613048, 2024). "Less commonly, patients experienced infusion site reactions, hyperglycemia, increased insulin requirements, gastrointestinal distress, headaches, hearing loss, tinnitus, dizziness, urinary tract infections (UTIs), weight changes, and altered appetite." (PMID 38765324, 2024). "The study involves optimizing the casNP/insulin/C10 formulation, tracking delivery and release in diabetic mice, and evaluating its efficacy in controlling hyperglycemia (project number: 1R41DK131761-01)." (PMID 39065795, 2024). "Both type 1 diabetes (T1D) and T2D are characterized by hyperglycemia, high levels of glucose within the blood, and alterations to beta cell function, insulin secretion, cellular response to insulin, or both." (PMID 39033292, 2024). "This delivery system is distinguished by its excellent insulin-loading capacity (65 wt%), biocompatibility, bioavailability (24.1%), and insulin protection under severe circumstances, and hyperglycemia-induced drug release." (PMID 38167129, 2024). "IL-6 also activates suppressor of cytokine signaling (SOCS) proteins, which inhibit insulin signaling and glucose uptake, worsening hyperglycemia." (PMID 39857603, 2024). "The findings of the study showed that more than one-third (34.1%) of the patients who received steroid developed hyperglycemia, and among those who required insulin, about 70.7% of patients had an insulin requirement of more than >17 units." (PMID 38510914, 2024).
Hyperglycemia (continued). "Our findings identify the succinate/SUCNR1 axis as an amplifying route for insulin secretion in response to hyperglycemia." (PMID 38713514, 2024). "Proinflammatory cytokines released during asthma exacerbations can disrupt insulin sensitivity and alter lipid metabolism, thereby contributing to dyslipidemia and hyperglycemia." (PMID 39201554, 2024). "In early stages, most statements and guidelines recommended insulin injections to control hyperglycemia." (PMID 38755442, 2024). "In our pancreas-liver MPS, both glucose utilization and insulin response declined over time (hyperglycemia), indicating its potential for studying glucose dysregulation and beta-cell dysfunction in vitro." (PMID 39025915, 2024). "Continuous monitoring of blood glucose levels is essential to allow for timely adjustments in insulin therapy, thereby preventing both hyperglycemia and hypoglycemia." (PMID 39199594, 2024). "By using this feature, the SmartAdjustTM technology can add up to 30% more insulin to a suggested bolus to address hyperglycemia." (PMID 38785359, 2024). "In conclusion, hyperglycemia potentiates ucOC-induced insulin secretion in β-cells by opening VDCCs and upregulating GSIS genes." (PMID 39125265, 2024). "They describe how exercise improves insulin sensitivity and reverses the molecular processes of hyperglycemia by strengthening the insulin signaling pathway, activating the AMP-activated protein kinase (AMPK) pathway, and having anti-inflammatory effects." (PMID 39290329, 2024). "DM is a metabolic disease characterized by hyperglycemia, which results from insufficient insulin secretion, resistance to insulin action, or a combination of both factors." (PMID 39415841, 2024). "In both mouse models, we examined the T2DM phenotypes, including hyperglycemia and insulin resistance, as detected by glucose tolerance and insulin tolerance tests." (PMID 38946582, 2024). "As a result, it leads to hyperglycaemia, an increase in blood glucose levels due to decreased insulin secretion." (PMID 39458491, 2024). "Furthermore, sustained hyperglycemia that mimics diabetic glucose levels has been shown to cause a significant beta-cell loss in cats and in human β-cells, and transcripts for insulin signaling in muscle tissue were reported to be decreased in obese cats and humans." (PMID 39684905, 2024). "These components exhibit efficacy in postprandial hyperglycaemia, which increase more gradually over time, and enhance insulin sensitivity." (PMID 39229589, 2024). "Take neurovirulent EV71 as an example; this study illustrates the reduction of hyperglycemia using insulin alone was observed to significantly lower viral load and mitigate the pathological manifestations of encephalitis in the EV71-infected mice." (PMID 38773966, 2024). "Insulin action in osteoblasts stimulates mitosis, inhibits apoptosis, and prevents hyperglycemia's deleterious effects on bone formation." (PMID 38378872, 2024). "Taken together, the current study showed that GFL has superior efficacy compared to LF in alleviating hyperglycemia and fatty liver by improving hepatic insulin signaling and inhibiting hepatic lipogenesis and inflammation in diabetic mice." (PMID 39796441, 2024). "When mice were exposed to environmental TCDD at a dose of 20 ng/kg, the hyperglycemia induced by a high-fat diet and the reduction in plasma insulin levels induced by glucose were intensified." (PMID 38251002, 2024). "T2DM is the most prevalent type, with a longer disease course, and is characterized by hyperglycemia due to a decrease in insulin secretion by the pancreas." (PMID 39598478, 2024). "Instead, streptozotocin has long been a reliable method of inducing severe hyperglycemia, while maintaining normal body weight and insulin sensitivity." (PMID 38786744, 2024). "Insulin is the safest and most effective option to treat hyperglycemia in the immediate post-transplant period." (PMID 38337487, 2024).
Hyperglycemia (continued). "Cell resistance to insulin uptake leads to an increase in circulating blood glucose levels (hyperglycemia) and higher insulin secretion for a compensatory effect." (PMID 39000383, 2024). "The direct impact of hyperglycaemia on skeletal muscle includes the dysregulation of glucose and lipid metabolism, leading to insulin resistance, muscle atrophy, and altered muscle fibre composition." (PMID 39204115, 2024). "Hyperglycemia in diabetic conditions can be reduced by the action of insulin on glucose uptake in muscle and adipose tissue." (PMID 39605919, 2024). "We previously reported that HFD-fed heterozygous mIR (mIR/HFD) mice exhibited an insulin-resistant phenotype, showing hyperglycemia even in the fasted state." (PMID 38604598, 2024). "The persistent hyperglycemia despite high insulin doses suggests a significant impairment in insulin sensitivity, possibly caused by capivasertib." (PMID 39099917, 2024). "This autoimmune state in diabetic patients can destroy insulin-producing cells (β cells) and lead to hyperglycemia due to decreased insulin production." (PMID 38344477, 2024). "Recent research has highlighted the significant role of continuous apelin infusion in improving serum insulin levels and reducing hyperglycemia in rats with T2DM induced by a high-fat diet and STZ." (PMID 38622732, 2024). "From the biochemical examination, PLAGL1 overexpression mice group showed similar body weight as other groups, significant higher fast blood glucose and lower fast blood insulin level, indicated hyperglycemia." (PMID 39365284, 2024). "In response to insulin resistance, β-cells increase insulin production, which gradually leads to their destruction, as well as to hyperglycemia and eventual insulin dependence." (PMID 39334905, 2024). "It increases insulin secretion by pancreatic beta cells, lowering waste product accumulation within the body due to prolonged hyperglycemia." (PMID 38565861, 2024). "The pathophysiology of GDM involves insulin resistance that exceeds the body's compensatory insulin secretion, leading to hyperglycemia." (PMID 39463673, 2024). "Insulin therapy to control hyperglycemia and acidosis is critical, and vomiting can be managed with antiemetics and prokinetic agents like metoclopramide or domperidone, which are more effective in patients with diabetic gastroparesis." (PMID 39759658, 2024). "HFD-fed diabetic mice had higher serum total cholesterol (TC), triacylglycerol (TG) and insulin levels, hyperglycemia, and gained weight faster than diabetic mice fed normal diet." (PMID 38790051, 2024). "Surgical intervention including esophagectomy produces oxdative stress and inflammatory cytokines, which decreases insulin secretion and increase insulin resistance, resulting in hyperglycemia." (PMID 38431548, 2024). "Thisresulted in an initial period of hyperglycemia and led to a compensatory increase in themealtime insulin to manage glycemia during the first couple of weeks." (PMID 38224978, 2024). "T2D is a chronic and progressive disorder characterized by persistent hyperglycemia resulting from inadequate insulin secretion or utilization." (PMID 39469399, 2024). "Broccoli increases insulin sensitivity, reduces glucose production, and inhibits ROS formation and the activity of α-amylase and α-glucosidase, contributing to lowering hyperglycemia." (PMID 39519546, 2024). "In response to a meal, insulin secreted by the pancreas gets bound to the insulin autoantibodies and thus becomes inactive, leading to a transient hyperglycemia." (PMID 38926797, 2024). "Even worse, prolonged hyperglycemia-induced glucotoxicity can lead to β-cell death and dysfunction, and impede insulin production." (PMID 39202492, 2024). "The resulting glucotoxicity and lipotoxicity exacerbate the dysfunction of β-cells to secrete insulin in response to hyperglycemia or oral hypoglycemic agents." (PMID 38681772, 2024).